RBM5 (RNA binding motif protein 5)
Diseases named in the same sentence as RBM5 in open-access papers (continued):
Sharing a sentence is not in itself a finding about the gene and the disease.
tumor (49 papers, 2002 to 2026). "In the same line, downregulation of HNRNPM and RBM5 is associated with an increase in tumor aggressiveness." (PMID 37880792, 2023). "We recently demonstrated that RBM5 expression in C4 significantly altered the expression of 11 of these SCLC-associated genes in a way which would suppress tumor growth." (PMID 28662214, 2017). "Collectively, these data suggest that reduced RBM5 expression is associated with increased cancer risk and that RBM5 is a tumour suppressor." (PMID 29176597, 2017). "RNA binding protein 5 (RBM5) is a candidate tumor suppressor gene and encodes a nuclear RNA binding protein." (PMID 26930047, 2016). "In order to further confirm the fact and investigate the potential molecular mechanism underlying the tumor suppressive activity of RBM5, we observed the effects of RBM5 on A549 cell growth and apoptosis with RBM5 overexpression." (PMID 22866867, 2012). "Furthermore, we revealed that poor clinicopathological features and high tumor recurrence rate are significantly associated with a low expression of RBM5 and high expression of KRAS." (PMID 23425895, 2013). "In addition, we also noted that increased expression of TNF-α and cleaved caspase-8 was associated with the RBM5 overexpression in tumor tissues." (PMID 23721095, 2013). "The tumour-suppressor RBM5 controls an exon network regulating apoptosis, yet its molecular mechanism is elusive." (PMID 41929118, 2026). "miR-483-5p overexpression was demonstrated to promote tumor growth in PCa cells by suppressing RBM5, a tumor suppressor gene that modulates apoptosis by regulating the alternative splicing of critical apoptotic mediators, including FAS and caspase-2." (PMID 41136394, 2025). "We wanted to see if the CHIP-mediated degradation of eIF2α and upregulation of RBM5 contribute to tumor suppression." (PMID 38272235, 2024). "Mechanistically, RBM5 is thought to promote tumor growth through a feedback loop involving miR-432–5p and β-catenin." (PMID 39132499, 2024). "Taken together, these results indicated that when CHIP levels increased in A549 cells, eIF2α degradation was promoted, and the expression of tumor suppressor RBM5 was upregulated and thus suppressed tumor proliferation." (PMID 38272235, 2024). "Specifically, HNRNPM is implicated in the adaptation to a hypovascular environment; while RBM5 expression inversely correlates with KRAS levels and is associated with clinicopathological features and appears to promote tumor progression." (PMID 37880792, 2023). "The data from GEPIA database indicated the expression of RBM5 was downregulated in LUAD tumor tissues compared with control tissues." (PMID 36193508, 2022). "There is evidence that overexpression of RBM5 is involved in the regulation of AS and suppresses tumor growth by controlling apoptosis and cell cycle." (PMID 35158863, 2022). "It was reported that RBM5 downregulation was involved in GC progression, behaving as a tumor suppressor gene in GC." (PMID 35515139, 2022). "RBM5, a tumour suppressor gene and splicing factor, improves the production of mRNAs by recognizing incorrect 3′splice sites of epidermal growth factor receptor (EGFR) pre-mRNA, thereby inhibiting the proliferation of tumour cells." (PMID 35552415, 2022). "Above all, RBM5 inhibits proliferation, affects cell cycle progression, and promotes apoptosis, which are generally considered components of the tumor-suppressing process." (PMID 33718153, 2021). "RBM5 changes normal bronchial cells, promotes the development of tumor and changes the curative effect in patients." (PMID 33718153, 2021). "Compared with tumor cell lines, the expression level of RBM5 is higher in normal tissues, indicating that RBM5 has an anti-tumor effect." (PMID 33718153, 2021). "Several investigators reported that increasing RBM5 levels via injection of vector plasmids in immunocompromised nude mice inoculated with A549 or BEAS-2B cancer cells inhibited tumor growth." (PMID 32765218, 2020).
tumor (continued). "Another factor tightly linked with tumor progression is the RNA-binding motif protein 5 (RBM5), whose gene is named LUCA-15 or H37, which is a direct modulator of cell cycle." (PMID 31205749, 2019). "The RNA binding motif 5 (RBM5) is one of the component genes in the 3p21.3 tumour suppressor region." (PMID 29176597, 2017). "RBM5 has been shown to suppress anchorage-dependent and anchorage-independent growth in A9 mouse fibrosarcoma cells and to inhibit their tumour forming activity in nude mice." (PMID 29176597, 2017). "In fact, accumulating data suggest that RBM5 was a tumor suppressor and inhibited tumor growth or progression by triggering apoptosis and inducing cell cycle G1/S arrest." (PMID 28061901, 2017). "Here we demonstrate, for the first time, an in vivo role for RBM5 as a tumour suppressor in the mouse lung." (PMID 29176597, 2017). "The “T2” subline was derived from a pool of transfected cells, and had RBM5 expression levels comparable to non-tumor lung tissue, while the “C4” subline was derived from a single transfected cell, and had 6-fold higher levels of RBM5 than the T2 subline." (PMID 28662214, 2017). "Of the reported critical genes in tumors, RBM5 was a tumor suppressor and enhanced tumor cell apoptosis in a list of tumors." (PMID 28061901, 2017). "It has been confirmed that RBM5 overexpression contributed to the retardation of the tumor growth and cell death in A549 xenografts in previous studies." (PMID 26923134, 2016). "Then, transplanted tumor models of A549 cells on BALB/c nude mice were established and treated with the recombinant plasmids carried by attenuated Salmonella to induce RBM5 overexpression in tumor tissues." (PMID 26923134, 2016). "RNA binding motif 5 (RBM5) is a tumor suppressor gene, which inhibits tumor cells’ growth and enhances chemosensitivity through inducing apoptosis in our previous studies." (PMID 26923134, 2016). "In agreement with above cell culture findings, RBM5 overexpression in tumor xenografts induced LC-3 and LAMP1 localization, indicating that RBM5 induced autophagic flux in vivo." (PMID 26923134, 2016). "RBM5 expression was significantly higher in RBM5 group compared to the control group, suggesting that the RBM5 was efficiently delivered into tumor xenografts and overexpressed by attenuated Salmonella in vivo." (PMID 26923134, 2016). "LUST (LUCA-15-Specific Transcript) is mapped to the antisense strand of gene RBM5 (3p21.3) that functions as a putative tumor suppressor." (PMID 26378581, 2015). "Although several studies found that the molecular mechanism of RBM5 tumor suppression involved cell proliferation inhibition, the precise mechanisms underlying such inhibition have been poorly understood." (PMID 25441176, 2014). "In this study, we established a novel animal model to determine RBM5 function in vivo, and concluded that RBM5 inhibited tumor growth in mice by inducing apoptosis." (PMID 23721095, 2013). "Tumor recurrence, analyzed by the Kaplan-Meier method, suggested that underexpression of RBM5 had a greater incidence of recurrence than overexpression (P=0.033)." (PMID 23425895, 2013). "The mice were treated with the recombinant plasmids carried by attenuated Salmonella to induce the overexpression of RBM5 in tumor tissues." (PMID 23721095, 2013). "The tumor suppressor gene, RNA binding motif 5 (RBM5) (also called Luca15 or H37), is one of the ∼45 genes located in the 370 kb tumor suppressor locus on chromosome 3p21.3." (PMID 23425895, 2013). "Together with several lines of in vitro evidence on its capacity to control cell cycle progression and apoptosis, RBM5 has been proposed as a putative tumour suppressor." (PMID 23935508, 2013). "RNA binding motif 5 (RBM5) is a tumor suppressor gene that regulates cell proliferation, differentiation and apoptosis through pre-mRNA splicing of related genes." (PMID 23425895, 2013).
tumor (continued). "All of these findings suggest that patients with lower levels of RBM5 have a poor prognosis, possibly due to tumor progression, metastasis, and resistance to cancer therapy." (PMID 23158838, 2012). "Tumor suppressor activity of RBM5 was also examined in the A549 xenograft model treated with pcDNA3.1-RBM5 plasmid carried by attenuated Salmonella typhi Ty21a." (PMID 22866867, 2012). "More importantly, we showed that accumulative and stable overexpression of RBM5 in the A549 xenograft BALB/c nude mice model significantly inhibited the tumor growth rate in vivo as compared to that in the control." (PMID 22866867, 2012). "To further determine the relationship between RBM5 gene and tumor growth, we performed the proliferation assay in A549 cells to explore the effect of RBM5 overexpression on proliferation of tumor cells." (PMID 22866867, 2012). "The data from the current study suggest that expression of RBM5 mRNA and protein is worth further evaluation as a biomarker for tumor diagnosis." (PMID 22537942, 2012). "RNA binding motif 5 (RBM5) is a tumor suppressor gene that modulates apoptosis through the regulation of alternative splicing of apoptosis-related genes." (PMID 22537942, 2012). "The expression of RBM5 mRNA and protein was decreased significantly in adenocarcinoma tissues compared to that in the non-tumor tissues." (PMID 22866867, 2012). "RBM5 plays an important role in the induction of cell cycle arrest and apoptosis through pre-mRNA splicing of multiple target genes, and inhibits tumor transformation and the progression of several malignancies, including NSCLC." (PMID 22537942, 2012). "Recent studies have indicated that the nuclear RNA-binding protein RBM5 has the ability to modulate apoptosis and suppress tumor growth." (PMID 23158838, 2012). "The attenuated Salmonella typhi Ty2la bacteria approaches in our study demonstrated an important role of RBM5 in inhibition of tumor growth." (PMID 22866867, 2012). "The increasing evidence showing the potential molecular mechanism of tumor suppressive activity of RBM5 involves both cell cycle arrest and apoptosis." (PMID 23158838, 2012). "This suggested that expression of RBM5 protein was maintained and continued to be effective in suppressing tumor growth throughout the whole process." (PMID 22866867, 2012). "Transcription-induced chimeras of the neighboring genes RBM6 and RBM5 were identified in human tumour tissues." (PMID 17908320, 2007). "Thus, RBM5 acts as a dual-action spliceosome gatekeeper that couples helicase activation with physical stalling to enforce tumour-suppressive alternative splicing programmes." (PMID 41929118, 2026). "RBM5 (RNA Binding Motif 5) has been identified as a tumor suppressor in the lung." (PMID 35004299, 2021). "RBM5 was observed to promote cell apoptosis and retard tumor growth." (PMID 33584809, 2020). "Over-expression of RBM5 also managed to decrease tumor growth in vivo." (PMID 31205749, 2019). "It was shown that RBM5 was dramatically reduced in tumor tissues compared to paratumor tissues." (PMID 28061901, 2017). "Our results provide evidence that RBM10 expression, in RBM5-null tumors, may contribute to tumor growth and metastasis." (PMID 28662214, 2017). "RBM5 was a RNA-binding motif protein and was reported as a tumor suppressor." (PMID 28061901, 2017). "Previous studies have shown tumor-suppressor properties for both RBM5 and RBM10." (PMID 28662214, 2017). "Studies using human cancer specimens and cell lines suggest a role for RBM5 as a tumour suppressor." (PMID 29176597, 2017). "The genes FHIT and RBM5 are suggested as tumor suppressor genes." (PMID 25860936, 2015).
tumor (continued). "We demonstrate that EGFR expression is regulated by RBM5 in vivo and in vitro in a direct or indirect way, and that may be one of the predominant mechanisms by which RBM5 mediated tumor suppression." (PMID 25441176, 2014). "However, the precise mechanism by which RBM5 mediated tumor suppression still remains to be clarified." (PMID 25441176, 2014). "Overexpression of RBM5 enhanced the apoptosis in tumor xenografts." (PMID 23721095, 2013). "In addition, the association of RBM5 and KRAS expression with clinicopathological parameters and tumor recurrence was analyzed." (PMID 23425895, 2013). "Furthermore, how to deliver a vector overexpressing RBM5 to the tumor-specific part is the key point for the study in vivo." (PMID 23721095, 2013). "In addition, multiple protein isoforms of RBM5 exist, each possessing apoptosis modulatory activity, a function consistent with tumor suppressor activity." (PMID 23721095, 2013). "In addition, overexpression of RBM5, which is also involved in the regulation of alternative splicing, was shown to inhibit tumor growth and reduced the metastatic potential." (PMID 22866867, 2012). "This study aims to explore the potential utility of RBM5 as a tumor diagnosis marker in NSCLC." (PMID 22537942, 2012). "Thus, it is likely that the ability to modulate apoptosis is the central to the putative tumor suppressor activity of RBM5." (PMID 23158838, 2012). "Thus, it is likely that the ability to modulate apoptosis is central to the putative tumor suppressor activity of RBM5." (PMID 22866867, 2012). "In the present study, expression levels of RBM5 protein were reduced in NSCLC compared with the non-tumor tissues, suggesting that RBM5 could play a role in suppression of NSCLC development or progression." (PMID 22537942, 2012). "In a very small cohort of eleven specimens, it was observed that the six tumor samples with the most significantly reduced RBM5 mRNA levels were of the squamous type whereas three of the nine with less significantly reduced RBM5 mRNA levels were adenocarcinomas." (PMID 22866867, 2012). "In this study, we found that reduced expression of RBM5 protein was associated with lymph node metastasis of NSCLC, indicating that RBM5 may play a potential role in the suppression of tumor metastasis." (PMID 22537942, 2012). "Although the mechanisms of RBM5-mediated tumor suppression remain unknown, recent studies suggest that RBM5 is involved in the regulation of the apoptosis pathway." (PMID 23158838, 2012). "Our group and others have successfully identified novel apoptotic controlling genes including LUCA15/RBM5 a novel tumor suppressor gene, fau (Finkel–Biskis–Reilly murine sarcoma virus (FBR-MuSV) associated ubiquitously expressed gene), vATPase, protein phosphatase 4 (PP4), Toso and RACK-1." (PMID 19698770, 2009). "Numerous functions have been ascribed to RBM5 gene products, including tumor suppression, apoptosis modulation, cell cycle regulation and RNA binding, however, the mechanism of action of the full-length RBM5 protein is only just beginning to be delineated." (PMID 17908320, 2007). "However, it is unclear whether RBM5 regulates BC cell proliferation and tumor progression via AS-NMD." (PMID 38201567, 2023). "In addition, it has been demonstrated that RBM5 acts as tumor suppressor in different cancers." (PMID 36193508, 2022). "Thus, our in vivo study, which demonstrated the anti-tumor effect of RBM5 significantly, may be more convincing and promising, which demonstrated the anti-tumor effect of RBM5 significantly." (PMID 22866867, 2012). "Conversely, certain SFs, including QKI, RBM5, RBM6, and RBM10, act as tumor suppressors and exhibit anti-cancer characteristics." (PMID 39004679, 2024). "Although RBM5, RBM17, and RBM39 belong to the RNA-binding motif (RBM) family protein, their regulatory role in tumor progression is largely variable." (PMID 38216972, 2024).
tumor (continued). "RBM5 (RNA-binding motif protein 5) and RBM6 (RNA-binding motif protein 6) were initially reported as tumor suppressors." (PMID 33584809, 2020). "Altogether, these studies highly suggest that RBM10, similar to RBM5 and RBM6, possesses a tumor suppressive function via different mechanisms." (PMID 32947864, 2020). "RBM5 and RBM10 also share functional similarities, and both have tumor-suppressor properties in various cancer cell lines." (PMID 28662214, 2017). "It has been reported that the reduced RBM5 and USP15 expressions result in tumor cell proliferation and induce tumor cell apoptosis, respectively." (PMID 26897165, 2016). "RBM5 (RNA-binding motif protein 5, also named H37/LUCA-15) gene from chromosome 3p21.3 has been demonstrated to be a tumor suppressor." (PMID 23721095, 2013). "RBM5 (RNA-binding motif protein 5, also named H37/LUCA-15) gene from chromosome 3p21.3 demonstrated tumor suppressor activity." (PMID 22866867, 2012). "Semi-quantitative reverse transcription-polymerase chain reaction (RT-PCR) and Western blotting were performed to detect expression of mRNA and protein, respectively, of RBM5, EGFR and KRAS in 120 paired non-tumor and tumor samples of NSCLC." (PMID 22537942, 2012). "Furthermore, the expression of RBM5 was significantly decreased in both NSCLC cell lines and tumor tissues compared with control." (PMID 36193508, 2022). "In tumor tissues, the upregulation of RBM10 and RBM5 may occur due to increased translation and protein stability, resulting in a significant increase in protein content, especially if RNA content remains unchanged or decreased." (PMID 33718153, 2021). "We confirmed an aberrant increase of cassette exon skipping in tumor specimens for PACSIN2 exon 8, DIAPH1 exon 2, FGFR1OP2 exon 4, MARK3 exon 16, DST exon 93, LMO7 exon 10, and RBM5 exon 7, whereas ADD3 exon 13, MAP3K7 exon 12, and MARK2 exon 15 were preferentially included in tumor specimens." (PMID 34202984, 2021). "Moreover, RBM5 and RBM10 have 401 common targets, indicating that RBM5 and RBM10 work together during the progression of tumor development." (PMID 33718153, 2021). "Together, these lines of evidence suggest that both RBM5 and RBM6 might play a tumor suppressive role in different types of cancers." (PMID 32947864, 2020). "Regarding CNAs present in 419 tumour suppressor genes, losses of the most common CNA tumour suppressor genes are found at 3p21.31 specified by genes RBM6 in 35 HRO-, RBM5 in 30 HRO-, LIMD1 in 28 HRO-, TCTA in 26 HRO- and at 3p22.2 by MLH1 in 33 HRO-tumours." (PMID 28486536, 2017). "We suggest that most, but not all, RBM5’s tumor-suppressor properties occur via this RBM5-RBM10v2 complex." (PMID 28662214, 2017). "Then, clinicopathological analysis indicated that downregulated RBM5 was significantly correlated with tumor stage (P = 0.004) but not with age (P = 0.068) or sex (P = 0.405)." (PMID 28061901, 2017). "Our study suggests that a combination of RBM5 overexpression and autophagic inhibitor could be a good approach to treat NSCLC and resensitize cells to anti-tumor drugs." (PMID 26923134, 2016). "Although the mechanisms of RBM5-mediated tumor suppression remain not quite clear, recent studies suggest that RBM5 is involved in the regulation of the mitochondrial apoptotic pathway and Bcl-2 family expression." (PMID 26923134, 2016). "When the bands were quantitatively compared, expression of RBM5 mRNA was found to be lower in tumor compared to the non-tumor counterpart in the majority of the paired samples (except in 9 of the 30 patients)." (PMID 22866867, 2012). "By comparison of normal and tumor expression of RBM5 mRNA and protein at a ratio of 2.0 as a cutoff point we found that expression of RBM5 mRNA and protein was significantly reduced in NSCLC vs. the non-tumor tissues (P = 0.037 and P = 0.03, respectively)." (PMID 22537942, 2012).